CRP (C-reactive protein)
Diseases named in the same sentence as CRP in open-access papers (continued):
Sharing a sentence is not in itself a finding about the gene and the disease.
spondyloarthritis (54 papers, 2012 to 2025). "A similar level of concordance between CT and CRP, both at baseline and after treatment, has been reported in patients with spondyloarthritis, supporting the potential of CT as a biomarker associated with treatment response." (PMID 41179899, 2025). "Studies indicate that CRP levels tend to be significantly higher in ISI patients compared to those with spondyloarthritis, supporting its diagnostic value." (PMID 41293359, 2025). "Increased levels of C-reactive protein, interleukins, and tumor necrosis factors are associated with the progression of spondylosis." (PMID 39685854, 2024). "An international, cross-sectional study that enrolled 2098 patients showed that age, HLA-B27 positivity, and CRP were independently associated with renal impairment (eGFR < 60 mL/min/1.73 m2) in patients with spondyloarthritis." (PMID 31818273, 2019). "The NRL was positively correlated with CRP in both diseases, although with a smaller effect size in Fibromyalgia patients (r = 0.14) compared with Axial Spondyloarthritis patients (r = 0.38)." (PMID 40564216, 2025). "A statistically significant difference was also observed in the mean CRP value between Fibromyalgia and Axial Spondyloarthritis patients (0.5 ± 0.2 vs. 0.6 ± 0.3; p = 0.01)." (PMID 40564216, 2025). "In the PREVENT study, adult patients fulfilling the Assessment of SpondyloArthritis International Society classification criteria for nr-axSpA with elevated CRP and/or MRI inflammation received secukinumab 150 mg or placebo." (PMID 37194094, 2023). "Spearman’s rank-order correlation coefficients and p-values for the relationship of thresholding-derived metrics (volume, number of lesions and high-sensitivity C-reactive protein to spondyloarthritis research consortium of Canada." (PMID 29179748, 2017). "Currently, CRP level is the sole biomarker used in spondyloarthritis." (PMID 41284991, 2025). "These patients had active spondyloarthritis with low CRP levels." (PMID 41179899, 2025). "Similarly, we are currently investigating the potential of ePROS in combination with semi-quantitative CRP results from point of care in RA and the TAP II devices for precise CRP measurement in patients with spondyloarthritis." (PMID 36461025, 2022). "In conclusion, traditional CVD risk factors, as represented by the ASCVD 10-year risk score, correlated with RDW and albumin in this spondyloarthritis cohort, and RDW was also associated with age, albumin, hemoglobin, race, HLAB27 status, CRP and statin treatment." (PMID 30363719, 2018). "In 210 early axial SpA patients from the German Spondyloarthritis Inception Cohort (GESPIC), elevated ESR levels at baseline (>20 mm/hr) and time-averaged elevated CRP levels over 2 years (>6 mg/L) were significantly associated with spinal radiographic progression during 2 years of follow-up." (PMID 25879956, 2015). "The inclusion of CRP and ESR in these cases would reduce the sensitivity for connective tissue diseases or spondyloarthritis." (PMID 39124816, 2024). "Then the study investigates the correlation between FAR and CRP/ESR, a subjective part of the criteria in evaluating disease activity, to search for the potential value of FAR in the assessment of spondyloarthritis." (PMID 36109740, 2022). "The correlation between FAR and traditional inflammatory biomarkers (CRP and ESR) as well as the capacity of FAR in identifying inflammation status supported FAR to be a new indicator in the assessment of inflammation in spondyloarthritis." (PMID 36109740, 2022). "The Chronic Arthritis group showed statistically significantly higher CRP and ESR mean values as compared to Connective Tissue Disease (p = 0.005) and to Spondyloarthritis (p = 0.003), respectively." (PMID 33207663, 2020). "Although the treatment escalation is based on CRP elevation, it is a marker of generalized inflammation rather than being specific for spondyloarthritis." (PMID 41284991, 2025).
spondyloarthritis (continued). "However, more profound research on the accuracy of CRP, ESR, and FAR in reflecting the disease activity of spondyloarthritis is required." (PMID 36109740, 2022). "In a cohort of 101 patients with chronic inflammatory arthritis, in which a significant positive correlation between C-reactive protein (CRP) values and QTc duration was demonstrated, we found that RA patients had a longer QTc when compared with both spondyloarthritis patients and healthy controls." (PMID 26798623, 2015). "Unexpected IFN-I downregulation, albeit is reminiscent to findings in experimental models of spondyloarthritis, was observed regardless of CRP and treatment modalities and may be indicative of dysregulated innate immune regulation in PsA pathogenesis." (PMID 38124740, 2023). "This study showed that the disease duration and CRP levels were not correlated with self-reported foot pain and function, which is consistent with results from a previous study conducted in people with spondyloarthritis." (PMID 35246222, 2022). "We believe that these discrepancies may be due to the fact that inflammation parameters, such as CRP, are not frequently high in spondyloarthritis, even if the patients are proven to have high disease activity from a clinical point of view." (PMID 35454961, 2022). "We considered spondyloarthropathy, but excluded this possibility when the ESR, CRP, HLA-B27, and joint X-ray and MRI were negative." (PMID 32991443, 2020).
bacterial meningitis (53 papers, 2009 to 2025). Inflammation of the membranes surrounding the brain and spinal cord due to a bacterial infection. "In conclusion, CRP in CSF is an excellent diagnostic marker for bacterial meningitis across all age groups within the European population, providing valuable diagnostic information in addition to CSF leukocyte count." (PMID 40636058, 2025). "Subsequently, we validated CRP in CSF as a diagnostic marker for bacterial meningitis in adult and pediatric patient populations." (PMID 40636058, 2025). "The search terms we used were ‘bacterial meningitis, ‘C-reactive protein’, ‘cerebrospinal fluid’, ‘diagnostics’, and ‘diagnostic accuracy’." (PMID 40636058, 2025). "We show that CRP in CSF is a highly accurate diagnostic marker for bacterial meningitis, demonstrating 100% sensitivity and 94% specificity in a clinical implementation cohort of patients with a suspected CNS infection." (PMID 40636058, 2025). "Three factors remained independent risk factors for predicting refractory bacterial meningitis: disturbance of consciousness, CRP ≥ 50 mg/L upon admission, and the isolate bacteria being G + bacteria." (PMID 37147568, 2023). "In previous studies, very high levels of C-reactive protein were associated with a higher rate of complications and sequelae of bacterial meningitis in children." (PMID 36210950, 2022). "Blood procalcitonin also showed higher diagnostic accuracy for detecting bacterial meningitis than other conventional biomarkers, including serum C-reactive protein and leukocyte count, CSF leukocyte and neutrophil count, and CSF protein and glucose levels." (PMID 34066811, 2021). "Current evidence suggests that blood PCT is a highly accurate diagnostic marker for pediatric bacterial meningitis and that it has higher diagnostic accuracy than blood CRP, WBC, and CSF parameters." (PMID 34066811, 2021). "At the second node, the presence of C-reactive protein, and complement C3 in the CSF are associated with the diagnosis of bacterial meningitis, and their absence points to enteroviral meningitis." (PMID 26040285, 2015). "Serum CRP is higher in bacterial than viral meningitis, and CRP of CSF is potentially useful diagnostic tool for diagnosis of bacterial meningitis." (PMID 23483792, 2012). "Several studies have shown procalcitonin to have a better diagnostic accuracy than CRP in differentiating between aseptic and bacterial meningitis." (PMID 23050153, 2012). "Finally, we evaluated the implementation of CRP measurements in CSF in our hospital and assessed diagnostic accuracy for the diagnosis of bacterial meningitis in routine clinical practice." (PMID 40636058, 2025). "We identified the following criteria as relevant for differentiating cases of bacterial meningitis from other causes of CSF pleocytosis: CSF cell count > 100 cells/μl, CRP > 5 mg/dl, altered mental status, nuchal rigidity, CSF protein > 100 mg/dl and elevated WBC count." (PMID 37656347, 2024). "In addition, some other studies showed that seizures, serum C-reactive protein levels, and disease severity were risk factors for hearing impairment after childhood bacterial meningitis." (PMID 30515129, 2018). "Four patients with a diagnosis other than bacterial meningitis presented with an elevated CRP in the CSF, of whom two had blood admixture in the CSF." (PMID 40636058, 2025). "Our findings suggest that the presence of three specific parameters—CRP >150 mg/dl, CSF glucose <6.75 mg/dl, and a CSF protein/glucose ratio >18.9—strongly indicates the need for surgical intervention in complicated bacterial meningitis." (PMID 40740821, 2025). "This is exemplified by a systematic review summarising the literature specifically for paediatric bacterial meningitis which reported pooled meta-analyses accuracy metrics for the best studied biomarkers, CRP, procalcitonin, IL6, IL8, TNF-alpha and ferritin." (PMID 40471671, 2025).
bacterial meningitis (continued). "C-reactive protein (CRP) in cerebrospinal fluid (CSF) was previously shown to be predictive for bacterial meningitis in patients with a suspected central nervous system (CNS) infection in an experimental study." (PMID 40636058, 2025). "The AUC of CRP in CSF for differentiating bacterial meningitis from all other patients in all cohorts combined, was 0.94 (95% CI: 0.89–0.98)." (PMID 40636058, 2025). "We used the CRP plasma/serum application on the Roche Cobas Pro to measure four samples from culture positive bacterial meningitis patients." (PMID 40636058, 2025). "CRP in CSF was measured in 103 adult patients from Denmark, which included 34 (33%) bacterial meningitis patients." (PMID 40636058, 2025). "In all bacterial meningitis patients CRP in CSF was elevated, including 8 patients with a CSF leukocyte count below 1000 cells/mm3." (PMID 40636058, 2025). "We showed that CRP levels in CSF, measured using a Luminex assay, alongside IL-6 and IL-1β, can accurately distinguish bacterial meningitis from other disorders in a cohort of 778 patients with suspected CNS infection, regardless of CSF leukocyte count." (PMID 40636058, 2025). "The AUC of CRP in CSF for differentiating bacterial meningitis from viral CNS infections was 0.92 (95% CI: 0.85–0.99)." (PMID 40636058, 2025). "The AUC of CRP in blood for differentiating bacterial meningitis from other diseases was 0.90 (0.83–0.98) and was significantly lower than CRP in CSF (p = 0.02)." (PMID 40636058, 2025). "Our study shows that the serum CRP level is useful as an adjunct test, significantly higher in bacterial meningitis compared to viral meningitis and this finding is consistent with existing literature." (PMID 41510242, 2025). "CRP in CSF proved to be a highly reliable marker for bacterial meningitis across all age groups in the European population, offering valuable diagnostic information in addition to CSF leukocyte count." (PMID 40636058, 2025). "We validated CRP measurements in CSF for the diagnosis of bacterial meningitis in a Danish cohort of patients with acute CNS infections, and a Dutch cohort of pediatric patients suspected of a CNS infection." (PMID 40636058, 2025). "CRP in CSF is a highly reliable predictor for bacterial meningitis, offering incremental value in addition to CSF leukocytes." (PMID 40636058, 2025). "The levels of lactate dehydrogenase (LDH) and high sensitivity CRP (hsCRP) increased in the CSF of bacterial meningitis patients compared with non-bacterial meningitis patients." (PMID 36864913, 2023). "Our study found that children with bacterial meningitis whose serum CRP was significantly elevated at the beginning of the disease were more likely to develop refractory bacterial meningitis, especially for those with CRP ≥ 50 mg/L." (PMID 37147568, 2023). "It is stated that serum CRP level is a better indicator for predicting bacterial meningitis because the level of this protein in CSF indicates only the degree of impairment of the blood-brain barrier." (PMID 35974935, 2022). "A2M along with IL-6 and C-Reactive-Protein (CRP) levels in the CSF can indicate blood-cerebrospinal fluid barrier (BCB) damage in bacterial meningitis as part of the acute phase reaction." (PMID 35401413, 2022). "A recent study in bacterial meningitis showed that NfL in bacterial meningitis was an independent predictor for unfavourable outcome, after correction for age, cranial nerve palsy, and high serum CRP levels." (PMID 35986031, 2022). "Two parameters, procalcitonin and C-reactive protein, appeared to have a good predictive value in bacterial meningitis." (PMID 34395616, 2021). "All patients with suspected bacterial meningitis should receive a basic laboratory panel including blood leukocyte counts, serum C-reactive protein CRP, and serum procalcitonin PCT." (PMID 33499920, 2021). "The proportion of patients with raised CRP level (1 mg/dL) was higher in bacterial meningitis than viral and TBM." (PMID 34020719, 2021).
bacterial meningitis (continued). "Age 40 years, rural residence, raised CRP, and all parameters in CSF analysis (raised WBC count, neutrophil count, protein, and ADA; and low CSF/blood glucose ratio) were associated with bacterial meningitis in the univariate analysis." (PMID 34020719, 2021). "In laboratory findings, WBC count was higher in viral and bacterial meningitis than tubercular meningitis, and the proportion of raised CRP levels was found higher in bacterial and tubercular meningitis than viral meningitis." (PMID 34020719, 2021). "Serum CRP is elevated in bacterial meningitis, and resolution of symptoms following treatment with antibiotics is slow in those with the highest CRP levels." (PMID 29706967, 2018). "Based on these results, the authors concluded that S–PCT performs better than CRP in the detection of bacterial meningitis." (PMID 29891780, 2018). "Currently, cerebrospinal fluid (CSF) analysis has been considered the gold standard for diagnosing bacterial meningitis, along with biomarkers like C-reactive protein (CRP) and white blood cell count (WBC)." (PMID 30388962, 2018). "Clinical history and CRP results of 10 cases classified as confirmed cases of bacterial meningitis according to the definitions of the World Health Organisation (WHO) Coordinated Invasive Bacterial Vaccine Preventable Diseases (IB-VPD) Surveillance Network." (PMID 28346504, 2017). "We did instead include c-reactive protein, that has been shown to be very sensitive as a supplemental parameter in order to differentiate viral from bacterial meningitis." (PMID 26303023, 2015). "Considerable peripheral leucocytosis (>10.000/mm3) and raised CRP level (>6) was significantly higher in our bacterial meningitis group in 52.1% and 74.4% of patients, respectively." (PMID 24803939, 2014). "Three parameters, CSF protein, neutrophil count, and CRP, appeared to have good predictive value in bacterial meningitis." (PMID 24803939, 2014). "The AUROC of PCT and CRP were 0.98 (95% CI, 0.83-1.0) and 0.81 (95% CI, 0.58-0.92), respectively; however, the small number of patients with confirmed bacterial meningitis (n = 18) limits the inferences from this study." (PMID 23830525, 2013). "CRP level that obtained, in 49 patients with bacterial meningitis and positive culture was (0-51000ng/ml)." (PMID 23483792, 2012). "Both CRP and procalcitonin have been evaluated to distinguish between viral and bacterial meningitis." (PMID 23050153, 2012). "Mean CSF CRP was 2.2 (0.4-4.74) in bacterial meningitis and 0.57 (0.12-2.72) in viral and WBC in CSF was (240-17500) in bacterial meningitis and (20-3200) in viral, that not sufficient useful to differentiate viral meningitis from bacterial." (PMID 23483792, 2012). "In one study in India, in 2001, CRP was measured in serum and CSF of 47 patients as a factor of rapid diagnosis of bacterial meningitis." (PMID 23483792, 2012). "A 2024 systematic review on biomarkers for the diagnosis of bacterial meningitis in children found that CRP levels in CSF could correctly distinguish viral from bacterial meningitis with a pooled AUC of 0.94 (95% CI: 0.92–0.97) in 454 patients." (PMID 40636058, 2025). "In addition, our study showed the better clinical benefits (fever, WBC and CRP) of a high PTA of meropenem therapy in children with bacterial meningitis (n = 18)." (PMID 36278190, 2022). "Biomarkers, like CRP, procalcitonin, or sTREM–1, may be useful for diagnosis and can help differentiate between viral and bacterial meningitis." (PMID 29891780, 2018). "Regarding laboratory findings, a left shift in peripheral white blood cell count, elevated serum PCT and C-reactive protein, CSF pleocytosis with predominance of polymorphonuclear leukocytes, and decreased glucose concentration are predictive of bacterial meningitis." (PMID 29891780, 2018).